IL6 (interleukin 6)
Diseases named in the same sentence as IL6 in open-access papers (continued):
Sharing a sentence is not in itself a finding about the gene and the disease.
asthma (continued). "Meta-analyses confirm significantly elevated serum IL-6 levels in asthma patients, correlating with disease severity, exacerbation frequency, and impaired lung function, while IL6R inhibition also demonstrates therapeutic benefits in T2DM patients." (PMID 41300562, 2025). "In a PM2.5-induced guinea pig model of asthma, Res reduced the expression level of IL-6 in bronchoalveolar lavage fluid." (PMID 40453664, 2025). "Elevated levels of inflammatory biomarkers, such as C-reactive protein (CRP) and IL-6, are reported in patients with severe asthma." (PMID 40823190, 2025). "Since asthma is mainly characterized by Th2 inflammation, multiple studies have focused on identifying the role of IL‐6 in asthma." (PMID 40568744, 2025). "Interleukin-6 (IL-6) plays a significant role in asthma pathogenesis through its effects on T cells and its association with pro-inflammatory responses." (PMID 39714726, 2025). "IL‐6 and IL‐18 play complex roles in both asthma and UC, demonstrating the intricate immune mechanisms involved." (PMID 40568744, 2025). "Several studies reported elevated levels of IL-6 in patients with respiratory diseases, such as asthma and COPD, in which the inflammatory status and the lung epithelial damage are well known." (PMID 39228520, 2024). "Of these, IL-6 is a target for a therapy that is in phase II clinical trials to treat severe asthma (clazakizumab), and IL-4R is a target for dupilumab, which has been tested in clinical trials for uncontrolled severe asthmatics." (PMID 39197446, 2024). "This endotoxemia triggers the activation of the nuclear factor-κB (NF-κB) pathway and upregulates the expression of IL-6 and TNF-α, thereby exacerbating inflammation associated with asthma." (PMID 39411430, 2024). "Due to increased blood levels of IL-17 and IL-6 were confirmed in patients with severe asthma, we further measured the plasma levels of IL-17 and IL-6 in inflammatory mice by ELISA." (PMID 38811424, 2024). "Similar to our findings, previous studies have also shown that exosomes derived from mast cells can release soluble mediators to stimulate the production of IL‐6 and IL‐8 from recipient cells, which further aggravates lung inflammation of asthma patients." (PMID 38938285, 2024). "Interleukin 6 potentiates IgE production by enhancing the effects of IL-4, and increased IL-6 synthesis in asthma patients has been well documented." (PMID 39703514, 2024). "The literature does, however, provide conflicting information about cytokine levels of IL-6 and IL-10 in AR, in adolescents with AR and asthma." (PMID 38398030, 2024). "Neutrophilic asthma, on the other hand, is characterized by non-T2 inflammation in the airways, involving Th1 and Th17 cells, as well as cytokines such as IL-6, IL-8, and TNF-α54." (PMID 39060348, 2024). "Elevated IL-17 levels prompt AECs to release IL-6 and IL-8, pro-inflammatory cytokines known to recruit neutrophils, exacerbating the severity of non-T2 asthma." (PMID 39538061, 2024). "This secretion of IL-6 is believed to be involved in cellular signaling during the development of asthma." (PMID 38388670, 2024). "It is well known that Th1/Th2 immune dysregulation is a common feature of asthmatic airway inflammation and that cytokines IL-4, IL-5, IL-6 and IL-13 produced by Th2 cells play an important role in asthma pathogenesis." (PMID 38579176, 2024). "Previous studies have found that the increase of IL-6 level is related to the severity of asthma, allergic rhinitis and other diseases." (PMID 38533318, 2024). "Increased levels of IL-6 and the soluble IL-6 receptor detected in the serum of severe asthma patients, as well as serum IL-6 levels, are independent predictors of future exacerbations among patients with severe asthma." (PMID 39194521, 2024). "In summary, this study provides valuable insights into the causal role of IL6 signaling downregulation in risk of respiratory diseases, especially COPD and asthma." (PMID 38898459, 2024).
asthma (continued). "As a significant association between the GG polymorphism of the IL-6 gene (− 174G/C) and mild asthma was found, while possessing at least one C allele, whether in a homozygous (CC) or heterozygous (CG) combination, independently predicts the likelihood of severe asthma." (PMID 38388670, 2024). "Asthma inflammation was characterized by elevated serum IL-6, increased lung cytokines (TNF-α, IL-6, IL-10), and higher fungal abundance confirmed by polymerase chain reaction (PCR)." (PMID 39484217, 2024). "New studies have revealed a correlation between heightened levels of IL-6 in the bloodstream and specific allergic conditions, including asthma, allergic rhinitis, and atopic dermatitis." (PMID 38388670, 2024). "TNF-α acts as a proinflammatory agent and exacerbates airway hyperresponsiveness in asthma, while IL-6 plays a role in both inflammation and Th2 cell differentiation." (PMID 39421735, 2024). "Asthma, like many other inflammatory diseases, increases interleukin (IL)-6 levels, which is the only proinflammatory cytokine known to pass from maternal to fetal circulation via the placenta." (PMID 37661216, 2024). "In patients with asthma, increased IL-6 and IL-1β levels are markers for systemic inflammation and are associated with reduced forced expiratory volume in 1 second (FEV1) and elevated acute exacerbations." (PMID 39439788, 2024). "In the early stage of asthma, the concentrations of IL-6 and IL-21 are likely insufficient to induce Th17 differentiation." (PMID 38629073, 2024). "Soluble IL-6Rα amplifies IL-6 signaling bronchial epithelial tissue, and high levels of this signaling have been observed in asthma patients with low sputum eosinophils." (PMID 39194521, 2024). "Systemic interleukin 6, a biomarker for metabolic dysfunction, is increased in patients with severe asthma and diabetes mellitus." (PMID 39272654, 2024). "The role of proinflammatory cytokines, such as IL-6, in modulating immune responses and exacerbating asthma-like symptoms underscores the importance of understanding the systemic effects of hematologic disorders on respiratory function." (PMID 38892971, 2024). "Our investigation into the Cc10−/− asthma mouse model revealed that lung DCs exhibited substantially higher mRNA expressions of IL-6 and TNF-α compared to wild-type counterparts, 24 h after allergen exposure." (PMID 39078462, 2024). "IL-6 cytokine promotes the proliferation and reactivation of mast cells and has been found to be related to asthma." (PMID 38302925, 2024). "The pro-inflammatory cytokine IL-6 can promote the differentiation and activation of T cells and the subsequent release of Th2 cytokines in allergic diseases such as asthma, AD, and AR." (PMID 39201342, 2024). "Increasing evidence has shown that Th17 cells secrete several types of cytokines (such as IL-17A and IL-6) to exert pro-inflammatory effects in autoimmune diseases, including asthma." (PMID 38579176, 2024). "In a randomized, double-blind, placebo-controlled trial assessing oligo-fucoidan’s role in asthma patients, it lowered serum IL-1b and IL-6 after 4 weeks and significantly reduced serum IL-8 after 24 weeks." (PMID 39728104, 2024). "Collectively, the distinct association of asthma with long-term comorbidities can be primarily attributed to neutrophilic patients, due to the elevated circulatory levels of TGF-β, IL-1β and IL-6 in this type of asthma." (PMID 38629073, 2024). "Several studies have shown that phosphorylation of MAPKs triggers inflammatory and immune responses by regulating the production of TNF-α, IL-6, and other inflammatory factors in asthma." (PMID 38745671, 2024). "According to the PPI analysis, inflammatory factor IL-6 was the highest among the related targets of SZYQD in the treatment of asthma." (PMID 38093206, 2023). "Higher serum IL-6 levels in adults with asthma have been found to correlate with increased body weight, decreased lung function, and an elevated risk of exacerbations." (PMID 37367676, 2023).
asthma (continued). "T2-low asthma is characterized by the activation of non-T2 inflammatory pathways, including helper T-lymphocytes type 1 (Th1) and/or Th17 cells, IL-6, IL-8, IL-17, and IL-22, and epithelial-derived cytokines." (PMID 37761964, 2023). "Asthma patients with obesity present with a distinct inflammatory endotype that includes increased IL-6, Th17 inflammation, and neutrophil infiltration." (PMID 37047327, 2023). "IL-6 and IL-8 are pro-inflammatory cytokines that contribute to disease severity in asthma and COPD and are therefore good therapeutic targets." (PMID 37111733, 2023). "Several pulmonary diseases, such as ALI, ARDS, asthma, COPD, and COVID-19 pneumonia, are associated with abnormal IL-6 and TNF-α expression." (PMID 37763673, 2023). "Studies have shown that ROS excess in airway epithelium increases asthma inflammation by releasing tumor necrosis factor (TNF) and IL-1, IL-6, and IL-8, especially with regard to severe asthma, asthma attacks, and asthma in obese subjects." (PMID 36671825, 2023). "Our findings related to the influence of asthma on the relationship between brain microstructure and CSF concentrations of S100B and IL-6 suggest a complex immune profile in those with asthma." (PMID 37377978, 2023). "The pleiotropic role of IL-6, which promotes Th2 and Th17 differentiation, plays a regulatory role for asthma and in our study, which has mostly patients with an allergic status (T2 inflammation), it seems to be concordant." (PMID 37371535, 2023). "In order to investigate the effect of ED on the inflammatory cytokine IL-6 in OVA-induced asthma mice, the IL-6 levels in the serum were analyzed." (PMID 37631100, 2023). "In another study, CM from asthma-derived primary eosinophils incubated with human bronchial fibroblasts (HBF) led to an increased expression of IL-6 and IL-8 in HBFs which was found to be specifically due to the release and activity of IL-1α from eosinophils." (PMID 36911735, 2023). "Smoking is another strong environmental trigger of macrophage activation and production of IL-17A, IL-6 and IL-8, leading to airway neutrophilia in asthma patients." (PMID 37189844, 2023). "Systemic elevation of IL-6 was seen in individuals with an exacerbation-prone asthma and increased production of IL-8 by bronchial epithelium cells involved in neutrophilic inflammation in asthmatic process." (PMID 37029363, 2023). "We observed a significant increase in the relative levels of IL-6 mRNA in group A compared to group N, indicating an upregulation of IL-6 in asthma." (PMID 38093206, 2023). "Using the signature, a sub-group of asthma patients specifically characterized by high IL-6 trans-signaling was identified who had frequent exacerbations and submucosal infiltration of T cells and macrophages." (PMID 38062491, 2023). "In terms of inflammatory cytokines, ATG5 was positively associated with TNF-α (rs=0.247, P < 0.001), IL-1β (rs=0.233, P = 0.001), IL-6 (rs=0.213, P = 0.003), and IL-17 (rs=0.154, P = 0.029) in adult asthma patients." (PMID 37644509, 2023). "This implicates that we cannot use this gene signature on nasal brushes to define IL-6-high asthma patients." (PMID 38062491, 2023). "IL-6 levels are also higher in the bronchoalveolar lavage fluid in type 2-low asthma compared to type 2-high asthma." (PMID 38062491, 2023). "Restoring the levels of ZFP36L1 and ZFP36L2 in primary bronchial epithelial cells from patients with severe asthma decreased the mRNA expression of IL6, IL8 and CSF2." (PMID 37928904, 2023). "ED also decreased inflammatory cells in the BALF of mice in an OVA-induced asthma model and reduced serum levels of IL-6." (PMID 37631100, 2023). "The Seinäjoki Adult Asthma Study31 also showed higher blood neutrophil levels and higher IL-6 levels, as well as more comorbidities alongside the reduced lung function in those with coexisting asthma and COPD." (PMID 36200674, 2023).
asthma (continued). "In asthma, IL-6 can be produced by primary lung epithelial cells, where allergic stimulus initiates the allergic inflammatory response." (PMID 37998734, 2023). "Sputum eosinophil counts were found to be significantly lower in asthma patients with high expression of the IL-6 high gene signature compared to those with low expression of the gene signature in bronchial biopsies." (PMID 38062491, 2023). "The levels of the inflammatory cytokine IL-6 were assessed in the serum of a mouse model of OVA-induced asthma." (PMID 37631100, 2023). "It has also been reported that IL-6 is overexpressed in bronchial epithelial cells in adults and children with asthma." (PMID 37173781, 2023). "Higher local airway IL-6 + sIL-6Rα signaling is observed in asthma patients with low sputum eosinophils." (PMID 38062491, 2023). "IL-6 and IL-8 production is generally increased in CRSwNP, as well as other inflammatory airway diseases such as asthma and COPD." (PMID 37176721, 2023). "Further, it was also found that there was an increased IL-6 concentration in fibroblasts upon co-culture with asthma-derived T-cells compared to controls." (PMID 36911735, 2023). "In vivo experiments consistently showed that QXD therapy reduced IL-6 expression in lung macrophages in an OVA-induced asthma mouse model." (PMID 38155957, 2023). "To further investigate the therapeutic effects of QXD, we evaluated its impact on IL-6 production in an OVA-induced asthma mouse model." (PMID 38155957, 2023). "In the current study, ATG5 was positively correlated with TNF-α, IL-1β, IL-6, and IL-17 in adult asthma patients." (PMID 37644509, 2023). "Patients with asthma exhibit elevated levels of IL-6 in their sputum and BALF compared to healthy subjects and compared to asymptomatic asthmatics, who already have higher serum IL-6 concentrations." (PMID 37569749, 2023). "Taken together, our results demonstrate that QXD treatment effectively decreased the PA concentration and inhibited IL-6 production in lung macrophages in an OVA-induced asthma mouse model." (PMID 38155957, 2023). "In obese patients, pro-inflammatory cytokines, such as IL-1β, IL-6, and TNFα, favor the pathogenesis of asthma." (PMID 36873818, 2023). "Because of these immune-regulatory roles, IL-6 is thought to be an important contributor to the pathogenesis of asthma and other pulmonary diseases with epithelial damage." (PMID 36945930, 2023). "The signature was significantly enriched in bronchial biopsies from asthma patients in comparison with non-asthma patients, which demonstrates functional enrichment of the IL-6 + sIL-6Rα pathway in asthma." (PMID 38062491, 2023). "IL-6 is also upregulated in serum and bronchoalveolar lavage fluid in asthma and COPD patients, suggesting the importance of GAIN in disease." (PMID 36543915, 2023). "Allergy status or asthma severity had no impact on measured inflammatory/oxidative markers, except for IL-6, which was higher in the allergic individuals with asthma vs. control (26.08 pg/mL vs. 9.92 pg/mL, p = 0.043)." (PMID 37371535, 2023). "Conversely, both the COPD (0.80–0.64 pg/mL, p = 0.025) and asthma (0.06–0.05 pg/mL, p = 0.007) groups exhibited significantly lower levels of interleukin-4 (IL-4) and interleukin-6 (IL-6) in EBC following hydrogen inhalation." (PMID 37873771, 2023). "To determine the effects of IL-31 on the expression of asthma-associated genes, we quantified the expression of genes associated with inflammation (IFNγ, TNF-α, IL-6, and IL-17) and Th2 responses (IL-4, IL-13, ARG1, MUC4, and MUC5AC)." (PMID 38081868, 2023). "In the Severe Asthma Research Program-3 (SARP3) adult cohort, IL-6 was a biomarker of exacerbation-prone asthma." (PMID 38292857, 2023). "The IL-6 + sIL-6Rα gene signature score was significantly increased in transcriptomes from bronchial biopsies in asthma patients compared to healthy controls." (PMID 38062491, 2023).
asthma (continued). "Following treatment of asthma with inhaled corticosteroids and long-acting β2-agonists, we observed a decrease in IL-6 and AGEs and an increase in DJ-1 levels." (PMID 37371535, 2023). "Obesity is associated with exacerbation of the inflammatory and immune response in asthma patients, depending on an increased synthesis of leptin, IL-6, and TNF-α." (PMID 37108123, 2023). "There are, however, patients with asthma characterized by non-T2 inflammation pathways, driven by IL-6, IL-1β, and IL23." (PMID 37371535, 2023). "Taken together, the interaction between eosinophils and fibroblasts results in an array of cytokine release (e.g., IL-6, IL-8, IL-11) that interestingly contributes to neutrophilic-inflammation in asthma." (PMID 36911735, 2023). "Further studies in mice showed that the NLRP3 inflammasome was required for asthma development and expression of the cytokines IL-13, IL-5, and IL-6 in obese mice fed an HFD." (PMID 35806353, 2022). "In the pathogenesis of asthma, with the activation of IL6 and Stat3 proteins, HIF-1α protein expression increases under the IL-6/Stat3/HIF-1α signaling pathway, which then promotes the apoptosis of spermatogenic cells, affecting sperm quality." (PMID 35620222, 2022). "Previous studies have found that IL-6 is related to the occurrence of allergic diseases such as asthma and atopic dermatitis, and it also has been shown that IL-6 can increase nasal secretion in patients with allergic rhinitis." (PMID 35368692, 2022). "A recent study suggests that pulmonary TNF-a, IL-1β and IL-6 action can affect airway functioning in asthma." (PMID 35335934, 2022). "Previous research by other members of the research team found that QF alleviated asthma exacerbation by decreasing the levels of IL-4, IL-6, and IL-13 in the serum and inflammatory cells in the lung tissue of RSV-infected asthmatic mice." (PMID 36081945, 2022). "Th17 cells can reportedly promote T cell activation and stimulate immune cells to produce diverse cytokines, among which IL‐17 and IL‐6 markedly impact the occurrence of asthma." (PMID 35959262, 2022). "During the acute stage of inflammation, IL-6 plays a central role in exacerbation of Th2-mediated diseases, including asthma and allergic airway inflammation." (PMID 36235405, 2022). "In patients with mild asthma, combustible cigarette smoking increases neutrophil counts, and IL-17A, IL-6, and IL-8 levels." (PMID 35626330, 2022). "To further characterize the impact of IL-6/TNF inhibition in asthma we used a high concentration of HDM, administrated intratracheally, to induce more abundant inflammatory response and tissue remodeling in mice." (PMID 35408882, 2022). "The IL-6 level was significantly increased in the asthma and ACO-a models compared with the control and COPD models." (PMID 36474247, 2022). "Anti-IL-6R mAb that blocks both mIL-6R and sIL-6R involves activating IL-6 trans-signaling to prevent allergen-induced asthma exacerbations." (PMID 35052792, 2022). "The IL-6 levels for the asthma patients with nocturnal symptoms were markedly higher than those for patients without nocturnal symptoms (7.45 ± 6.57 vs. 2.81 ± 1.49 pg/mL, p = 0.002)." (PMID 36505412, 2022). "Interleukin 6 (IL6) was recently identified as a promising biomarker for adult asthma in peripheral blood." (PMID 36140412, 2022). "Clinical observations in humans have been made correlating IL-6 levels with severity of systemic mastocytosis, asthma and related diseases involving mast cell activity." (PMID 35769569, 2022). "Here, we showed that Bcl10 mediated the LPS-induced expression of IL-6, IL-8 and TGF-β1 in bronchial fibroblasts, highlighting the pathogenic role of Bcl10-mediated signaling in promoting airway remodeling in severe asthma." (PMID 35885021, 2022). "Further studies are required to investigate the efficacy of simultaneous inhibition of TNF and IL-6 on the activity of other asthma-related markers that are crucial for airway remodeling." (PMID 35408882, 2022).